CERT1 (ceramide transporter 1)
Description:
Shelters ceramides inside its steroidogenic acute regulatory lipid transfer (START) domain and mediates their intracellular trafficking in a non-vesicular manner from the endoplasmic reticulum to the Golgi apparatus for conversion to sphingomyelin. Efficiently transfers ceramide molecules having long-chain fatty chains, but not those with very long acyl chains. Capable of transferring diacylglycerol, although with very low efficiency.
Synonyms: GPBP; StARD11; CERT; COL4A3BP; CERTL; MRD34; NEDHSF
Tractability: Small molecule: a structure with a bound ligand is known; it has a high-quality binding pocket. PROTAC: ubiquitination databases record sites on it; a small molecule that binds it is known.
Gene: Protein-coding gene on chromosome 5 (75,356,345 to 75,512,138, reverse strand). Ensembl gene ENSG00000113163.
Subcellular location: Cytoplasm; Golgi apparatus; Endoplasmic reticulum
Subcellular location (Human Protein Atlas): Golgi apparatus; Nucleoplasm
Pathways (Reactome):
Metabolism: Sphingolipid de novo biosynthesis
Gene Ontology:
Molecular function: ceramide binding; ceramide transfer activity; protein binding; ceramide 1-phosphate binding; lipid transfer activity; lipid binding
Biological process: ceramide metabolic process; ER to Golgi ceramide transport; intermembrane sphingolipid transfer; sphingomyelin biosynthetic process; immune response; intermembrane lipid transfer; sphingolipid biosynthetic process
Cellular component: cytoplasm; endoplasmic reticulum; endoplasmic reticulum-trans-Golgi network membrane contact site; Golgi apparatus; nucleoplasm; perinuclear region of cytoplasm; cytosol; endoplasmic reticulum membrane
Genetic constraint (gnomAD): Loss-of-function variants: 17 observed, 38.84 expected, observed/expected ratio (o/e) 0.44, 90% interval 0.3 to 0.66. The upper end of that interval is the gene's LOEUF score, 0.66, which puts it in group 2 of 6, group 1 being the genes least tolerant of losing a copy. Missense variants: 252 observed, 397.93 expected, observed/expected ratio (o/e) 0.63, 90% interval 0.57 to 0.7. Synonymous variants: 165 observed, 137.63 expected, observed/expected ratio (o/e) 1.2, 90% interval 1.05 to 1.36.
Homologues: Orthologues: chimpanzee CERT1 (100% identical), macaque CERT1 (99% identical), dog CERT1 (98% identical), mouse Cert1 (97% identical), rabbit CERT1 (96% identical), rat Cert1 (96% identical), guinea pig CERT1 (88% identical), tropical clawed frog cert1 (88% identical), pig CERT1 (86% identical), zebrafish cert1b (70% identical), Drosophila melanogaster cert (44% identical), Caenorhabditis elegans F25H2.6 (28% identical). Paralogues in human: PLEKHA8 (17% identical), PLEKHA3 (12% identical), GLTP (6% identical), GLTPD2 (6% identical), CPTP (4% identical).
Diseases named in the same sentence as CERT1 in open-access papers:
CERT1 is named in the same sentence as 50 diseases in open-access papers, as found by Europe PMC text mining. Sharing a sentence is not in itself a finding about the gene and the disease. The quoted sentences say what the papers report.
Intellectual disability (6 papers, 2019 to 2024). "A de novo mutation in CERT1, resulting in a gain-of-function effect, has been identified, providing insight into its role in intellectual disability." (PMID 39684889, 2024). "Mutations in the ceramide transporter CERT (CERT1), which is involved in sphingolipid biosynthesis, are associated with intellectual disability, but the pathogenic mechanism remains obscure." (PMID 36976648, 2023).
colon cancer (3 papers, 2021 to 2022). "To characterize CERT mutants in the absence of endogenous CERT, we used a HCT116 CERT1 knockout (KO) cell line, in which both alleles of CERT1 were disrupted in human colon-cancer-derived HCT116 cells." (PMID 34688657, 2021).
developmental delay (3 papers, 2020 to 2024). "In this study, we report that multiple de novo heterozygous variants in CERT1 caused an autosomal dominant developmental syndrome we named CerTra, which is characterized by various degrees of developmental delay, motor delay, cognitive impairment, behavioral abnormalities, and seizures." (PMID 36976648, 2023).
arterial hypertension (2 papers, 2023). "The results of the multivariable regression analyses revealed that the association between CERT1 score, and prevalent hypertension remained significant after adjusting for covariates in Model 1 (age and sex) and Model 2 (additionally for serum lipids)." (PMID 38137595, 2023). "After the full adjustment model, only CERT2 showed a significant predictive value for new- onset hypertension, while CERT1 became borderline significant." (PMID 38137595, 2023). "WC, HOMA-IR (surrogates of IDF diagnostic criteria for metabolic syndrome) and CRP (a marker of inflammation) were associated with CERT1, with the contribution of other parameters such as DBP/SBP, HDL-C and TG (i.e., arterial hypertension and dyslipidemia) being negligible." (PMID 37569827, 2023). "Adjusting for covariates, CERT1 and CERT2 showed no-longer-significant associations with hypertension prevalence, but only CERT2 predicted new-onset hypertension." (PMID 38137595, 2023).
Insulin resistance (2 papers, 2020 to 2023). Increased resistance towards insulin, that is, diminished effectiveness of insulin in reducing blood glucose levels. "Furthermore, visceral adiposity, insulin-resistance, and chronic low-grade inflammation represent, among those herein considered, the main factors capable of explaining the increased CERT1 in both OB-MetS− and OB-MetS+ subjects." (PMID 37569827, 2023).
autism (1 paper, 2023). Persistent deficits in social interaction and communication and interaction as well as a markedly restricted repertoire of activity and interest as well as repetitive patterns of behavior. "To determine the extent to which CERT1 mutations contribute to autism, we conducted a targeted de novo analysis interrogating the Simons Foundation Powering Autism Research (SPARK) initiative database, which includes genomic data from nearly 35,000 individuals with ASD." (PMID 36976648, 2023).
autism spectrum disorder (1 paper, 2020). A spectrum of developmental disorders that includes autism, and Asperger syndrome. "This is consistent with the fact that all the previously reported CERT1 variants that cause ID or autism spectrum disorder (ASD) were missense variants, and not truncation variants." (PMID 33347465, 2020).
COVID-19 (1 paper, 2023). A disease caused by infection with severe acute respiratory syndrome coronavirus 2. "Notably, in severe forms of COVID-19, ceramide synthases (CERS2, CERS4, and CERT1) responsible for the synthesis of Cer from Sph were upregulated." (PMID 37566018, 2023). "Furthermore, the expression levels of other enzymes associated with this pathway, such as ceramide synthase 2 (CERS2) and ceramide synthase 4 (CERS4), as well as the ceramide transfer protein (CERT1), were increased in severe COVID-19 patients." (PMID 37566018, 2023).
Diabetes (1 paper, 2023). "The aim of the present study was to evaluate CERT1 in a group of obese subjects without (OB-MetS−) and with (OB-MetS+) metabolic syndrome (according to the International Diabetes Federation (IDF) diagnostic criteria), compared to an age- and sex-matched normal-weight (NW) group." (PMID 37569827, 2023).
epilepsy (1 paper, 2025). A brain disorder characterized by episodes of abnormally increased neuronal discharge resulting in transient episodes of sensory or motor neurological dysfunction, or psychic dysfunction. "When cells are faced with starvation, PI4K2A and CERT can establish ER and autophagolysosomal contact sites, Recently, de novo missense variants in its gene CERT1 have been associated with a NDD with epilepsy and craniofacial dysmorphism." (PMID 39420677, 2025).
ischemic stroke (1 paper, 2026). A stroke disorder caused by obstruction of blood flow to the brain, due to thrombotic (local blood clot formation) or embolic (due to a blood clot or other material traveling from another site) event. "Patients with minor ischemic stroke had lower levels of C16:0-Cer, C18:0-Cer and CERT1 score with those with moderate and severe ischemic stroke." (PMID 41859096, 2026).
metabolic syndrome (1 paper, 2023). A cluster of metabolic risk factors for CARDIOVASCULAR DISEASES and TYPE 2 DIABETES MELLITUS. "Based on the results from the present study and the most recent biomedical literature on this topic, it is difficult to establish whether CERT1 may be an additional or substitutive marker to the currently used IDF diagnostic criteria for metabolic syndrome." (PMID 37569827, 2023). "Thus, based on the concept of CERT1, which is calculated by measuring specific ceramides and ceramide/ceramide ratios in the plasma, the clinical diagnosis of metabolic syndrome seems to be somewhat inaccurate in assessing CVD risk in an obese population." (PMID 37569827, 2023). "Thus, CERT1 seems to connote the state of obesity independently from the diagnosis of metabolic syndrome." (PMID 37569827, 2023). "In conclusion, the clinical diagnosis of metabolic syndrome seems to be inaccurate to assess CVD risk in the obese population; however, further studies are needed before considering CERT1 as an additional or substitutive biochemical marker in clinical practice." (PMID 37569827, 2023). "The aim of the present study was to evaluate the diagnostic value of CERT1 in a group of subjects with obesity without (OB-MetS−) or with (OB-MetS+) metabolic syndrome, compared to an age- and sex-matched group of normal-weight (NW) subjects." (PMID 37569827, 2023).
Stroke (1 paper, 2026). Sudden impairment of blood flow to a part of the brain due to occlusion or rupture of an artery to the brain. "Meanwhile, levels of C16:0-Cer, C18:0-Cer and CERT1 score were positively correlated with the National Institutes of Health Stroke Scale (NIHSS) and modified Rankin scale (mRS) score." (PMID 41859096, 2026).
infection (9 papers, 2011 to 2025). The state of being infected such as from the introduction of a foreign agent such as serum, vaccine, antigenic substance or organism. "To test this, we first investigated the localization of CERT1 during infection." (PMID 40689642, 2025).
neurodevelopmental disorder (4 papers, 2020 to 2026). A behavioral and cognitive disorder with onset during the developmental period that involves impaired or aberrant development of intellectual, motor, or social functions. "Ceramide transporter syndrome (CerTra syndrome) is a rare neurodevelopmental disorder caused by pathogenic variants in CERT1 gene encoding ceramide transporter (CERT)." (PMID 42051775, 2026). "Neurodevelopmental disorder with hypotonia, speech delay, and dysmorphic facies (NEDHSF) is a genetic disorder caused by a heterozygous mutation in the CERT1 gene (MIM604677)." (PMID 40182349, 2025). "The CERT1 gene, termed as COL4A3BP, was identified in three patients with neurodevelopmental disorders, possessing a p.Ser132Leu mutation in CERT1." (PMID 37892645, 2023).
neurological disease (1 paper, 2023). "Nonetheless, there has not been a systematic assessment of the mutational landscape of CERT1 in humans, and whether or how CERT1 mutations cause neurological disease remains to be proven." (PMID 36976648, 2023).
CERT1 also shares sentences with these, for which no sentence is quoted: cancer (24 papers); breast carcinoma (6); triple-negative breast carcinoma (6); tumor (6); ovarian carcinoma (4); neuroblastoma (3); Alzheimer disease (2); Chlamydia infection (2); chlamydial infection (2); infectious disease (2); lung carcinoma (2); neurodegenerative disease (2); amyloid (1); atherosclerosis (1); autoimmune disease (1); Autoimmunity (1); bladder carcinoma (1); cardiac failure (1); cholangiocarcinoma (1); Cognitive impairment (1); genetic disorder (1); glioma (1); hepatocellular carcinoma (1); hypertension (1); metabolic disease (1); Motor delay (1); Obesity (1); ovarian tumours (1); overnutrition (1); pancreatic adenocarcinoma (1).
A further 4 diseases each share a sentence with CERT1 in 1 paper.